CIP2A (cellular inhibitor of PP2A)
Diseases named in the same sentence as CIP2A in open-access papers (continued):
Sharing a sentence is not in itself a finding about the gene and the disease.
cancer (continued). "Cancerous Inhibitor of Protein Phosphatase 2A (CIP2A) is an oncogene that inhibits the tumour suppressor PP2A in many different cancers, including HNSCCs." (PMID 25474139, 2015). "Inhibition of CIP2A has been shown to decrease cancer cell viability, anchorage-independent growth and induce apoptosis 5,6." (PMID 25663244, 2015). "The depletion and overexpression of CIP2A via genetic methods decreased and increased cancer cell proliferation, respectively." (PMID 26560124, 2015). "And studies from other research groups reported that CIP2A overexpression were found in more than 70 % of other types of cancer patients." (PMID 26560124, 2015). "The clinical relevance of CIP2A, in the form of a prognostic marker, has been established for different human cancers." (PMID 25965834, 2015). "Taken together, the temporal expression pattern makes CIP2A as an ideal candidate for early cancer diagnosis." (PMID 26560124, 2015). "As CIP2A is overexpressed practically in all human cancer types, and its expression predicts poor patient survival in a dozen different cancers, it is an obvious drug target candidate protein." (PMID 25474139, 2015). "Our preliminary data showed that CIP2A regulates the phosphorylation status of mTOR, the target of rapamycin and finally affects the sensitivity of cancer cells to the treatment; however, how this process is actually executed has yet to be determined." (PMID 25109354, 2014). "It has been reported that CHK1 targeting reactivated PP2A tumor suppressor activity in cancer cells via CIP2A." (PMID 25015035, 2014). "Our current knowledge regarding the structure, function and regulation of CIP2A with particular emphasis on its “oncogenic nexus” opens up a possibility that CIP2A can be targeted in cancers." (PMID 25015035, 2014). "The presence of CIP2A protein was detected in 254 of the 280 (90.3%) cancer samples analyzed, and CIP2A protein expression was highly expressed in 184 of the 280 (65.7%) NPC patients examined." (PMID 24884612, 2014). "Based on the experimental evidence that CIP2A has a clinical relevance in the progression of the disease it has been regarded that CIP2A inhibitors have potential for use in the treatment in cancers." (PMID 25015035, 2014). "CIP2A is barely detectable in normal cells, but becomes specifically upregulated in a large variety of human cancers, hence its name [reviewed in Ref." (PMID 25566494, 2014). "Recently, CIP2A was found to be overexpressed at high frequencies in several types of human cancers." (PMID 24884612, 2014). "Accordingly, several agents that inhibit CIP2A have been identified, and some have demonstrated efficacy against different cancer cells." (PMID 25228280, 2014). "The central role of CIP2A in the “oncogenic nexus” allows CIP2A to mediate the effects (cancer cell phenotypes) of many anti-cancer drugs." (PMID 25015035, 2014). "Since CIP2A increases the proliferation of several cancer cells, they measured the effect of CIP2A on the doxorubicin-mediated inhibition of cell proliferation." (PMID 25015035, 2014). "Further studies designed to unravel the detailed molecular modification of CIP2A by tamoxifen and its application in other cancer cell types are warranted." (PMID 25228280, 2014). "The di-substituted erlotinib derivatives were tested for their ability to inhibit CIP2A and mediate cancer-cell proliferation." (PMID 25015035, 2014). "Considering the role of MMP9 and other members of MMP family in mediating invasion of tumor cells, inhibition of mRNA expression for MMP9 following depletion of CIP2A clearly indicated a direct effect of CIP2A in metastasis in this cancer." (PMID 25015035, 2014). "The high frequency of autoantibodies to CIP2A detected in the sera of cancer patients makes it a promising candidate for biomarker development." (PMID 25109354, 2014).
cancer (continued). "The review will try to understand the role of CIP2A (a) as a biomarker in cancers and evaluate the prognostic value of CIP2A in different cancers (b) as a therapeutic target in cancers and (c) in drug response and developing chemo-resistance in cancers." (PMID 25015035, 2014). "Studies have been undertaken in search of a lead compound for the development of CIP2A inhibitor for cancer therapies." (PMID 25015035, 2014). "The review describes the role of the PP2A-CIP2A oncogenic nexus in different organ type cancers and evaluates the clinical relevance of CIP2A “oncogenic nexus” in the context of therapeutic intervention." (PMID 25015035, 2014). "Knockdown of CIP2A enhanced radiation-induced apoptosis in cancer cells, and ectopic expression of CIP2A in cancer cells abolished radiation-induced apoptosis." (PMID 25015035, 2014). "In line with its role as an oncogenic protein in the transformation of cells and the progression of a disease, CIP2A has been shown to play a role in mediating a number of drug effects in cancer." (PMID 25015035, 2014). "In cancer cells, CIP2A upregulation is mediated by several oncogenic transcription factors, including Ets, Myc, and E2F, and often correlates with cancer aggressiveness and poor prognosis." (PMID 25566494, 2014). "Several recent studies have reported that silencing CIP2A decreases cell viability and suppresses anchorage-independent growth in several types of human cancer cells." (PMID 24884612, 2014). "In this study, we demonstrate the mechanism of action of the drug tamoxifen in ER-negative breast cancer cells, that is, induction of cancer cell apoptosis through CIP2A-dependent p-Akt downregulation." (PMID 25228280, 2014). "Consistent with previous findings on CIP2A expression in cancer, we found CIP2A mRNA expression in 93 of 104 (89.4%) cancer samples to be at least four times higher than in normal colon mucosal tissues." (PMID 24098375, 2013). "A natural product, rabdocoetsin B, has been reported to inhibit CIP2A level and reduce cancer cell proliferation." (PMID 24335617, 2013). "Cancers expressing low levels of CIP2A mRNA showed a weak staining for CIP2A protein, whereas cancers expressing high CIP2A mRNA levels showed a strong staining for CIP2A protein." (PMID 24098375, 2013). "Complete data sets (DFS, Tumor stages), comparing CIP2A mRNA expression in carcinoma to that in matched adjacent tissues, were available for 226 carcinomas." (PMID 24098375, 2013). "Taken together, these structurally unrelated agents show a common target in various cancer cells suggesting that CIP2A is a novel anti-cancer target." (PMID 22537901, 2012). "Chromatin immunoprecipitation, promoter mutagenesis and target specific siRNAs were then utilized to identify ETS1 as the transcription factor regulating EGFR-MEK1/2-dependent CIP2A expression in human cancers." (PMID 21445343, 2011). "Recent studies demonstrate that CIP2A displays many other activities, for instance, promoting stem cell self-renewal and giving cancer cells resistance to chemotherapeutic agents." (PMID 22075943, 2011). "Cancerous inhibitor of PP2A (CIP2A) is an oncoprotein expressed in several cancers, among them head and neck." (PMID 21610708, 2011). "In cancer specimens, however, we noted that cytoplasmic CIP2A was expressed both at low and at high levels." (PMID 21610708, 2011). "After its original cloning, and further functional characterization, CIP2A has been demonstrated to promote malignant cell growth by using various human cancer cell models." (PMID 21445343, 2011). "This makes CIP2A overexpression together with MEK1/2-ERK pathway activation as one of the most frequent alterations in human cancers." (PMID 21445343, 2011). "In order to estimate the relative transcriptional activity of the cloned CIP2A promoter fragment, we compared the luciferase activity of −1802CIP2ALuc to promoter/luciferase constructs known to be active in cancer cells." (PMID 21445343, 2011).
cancer (continued). "Together, these results provide concrete experimental evidence of ETS1 being the transcription factor mediating EGFR-MEK1/2 dependent regulation of CIP2A in cancer cells." (PMID 21445343, 2011). "CIP2A has been shown to promote proliferation and anchorage independent growth of various cancer cell lines and siRNA-mediated CIP2A depletion has been shown to very potently inhibit xenograft tumor growth." (PMID 21445343, 2011). "Here we present systematic analysis of contribution of potential gene regulatory mechanisms for high CIP2A expression in cancer." (PMID 21445343, 2011). "CIP2A promotes malignant cell growth and is over expressed at high frequency (40–80%) in most of the human cancer types." (PMID 21445343, 2011). "Notably, this anti-cancer effect was mediated through CIP2A deubiquitination, highlighting UCHL1 as a potential therapeutic target for future clinical investigation in GC." (PMID 41155583, 2025). "There is a positive correlation of CIP2A expression with tumor grade in many cancers." (PMID 41155727, 2025). "Notably, siRNA-mediated silencing of CIP2A has been shown to suppress the growth of xenografted tumors across multiple cancer types." (PMID 41154660, 2025). "CIP2A’s role in normal cell function appears to be less significant compared to its role in cancer cells, suggesting that targeting CIP2A signaling may be a safe approach for therapy." (PMID 41155727, 2025). "Therefore, CIP2A is emerging as a key regulator of cell survival and death, with its dysregulation contributing to cancer development and progression." (PMID 41362702, 2025). "The deactivation of PP2A in cancer is typically caused by mutations, post-translational modifications, or the increased expression of endogenous PP2A inhibitors, such as Suvar/Enhancer of zeste/Trithorax (SET) or cancerous inhibitor of PP2A (CIP2A)." (PMID 38184584, 2024). "Hence, CIP2A is a regulatory protein, and blocking CMA results in reduced CIP2A degradation, which has potential to prevent cancer development." (PMID 37450923, 2024). "As a long-lived protein, CIP2A is a potential therapeutic target among 12 different cancers." (PMID 38542160, 2024). "Collectively these data identify CIP2A as a very attractive cancer therapy target protein." (PMID 36854761, 2023). "The clinical value of the autoantibody responses to CIP2A/p90 and other TAAs might be further validated by more studies of different cancers." (PMID 36911405, 2023). "CIP2A/p90, in association with the oncogene H-Ras and through the recruitment of the MEK/ERK signaling pathway and c-Myc dephosphorylation by PP2A, is required for EMT in the progression of cancer." (PMID 36911405, 2023). "CIP2A inhibition also sensitizes cancer cells to large number of cancer therapies." (PMID 36854761, 2023). "For example, bioinformatics analysis of RAS and CIP2A-regulated phosphoproteomes revealed a significant overlap in their functional pathways, and strong synergies between CIP2A and RAS expression or KRAS mutation in cancer cell growth and survival were found." (PMID 37170215, 2023). "In about 10% of human cancers, PP2A is inhibited by genomic mutations, but the most prevalent mechanism for PP2A inhibition in cancer is overexpression of one of the numerous oncogenic PP2A inhibitor proteins such as CIP2A, PME-1, or SET." (PMID 36858798, 2023). "Since overexpression of SET and CIP2A induces cancer progression, and knockdown of SET and CIP2A inhibits tumor growth, the effects of anticancer drugs might be different in between cancer cells with SET and CIP2A and those with their knockdown." (PMID 37097392, 2023). "Collectively, these results validate the cancer relevance of the N-terminal head domain of CIP2A." (PMID 36854761, 2023). "How overexpression of SET and CIP2A proteins is induced in cancer cells remains to be investigated." (PMID 37097392, 2023).
cancer (continued). "We conclude that CIP2A inactivation renders cancer cells vulnerable to mitotic errors, which may represent a promising therapeutic target in combination with anti-mitotic agents or against chromosomally unstable or DNA-repair-deficient tumours." (PMID 37165191, 2023). "In addition, we performed gene silencing studies to assess the effects of the cancer-related gene-CIP2A in the progression of PD." (PMID 34984583, 2022). "Knockdown of CIP2A expression in various cancer cells inhibits the growth of xenografted tumors." (PMID 36098827, 2022). "Thus, SET/CIP2A-mediated PP2A suppression in cancer is particularly important for the induction of NELF-A phosphorylation." (PMID 36463234, 2022). "CIP2A overexpression enhances invasiveness and metastatic behavior of cancers and also acts as a useful marker in diagnosis, treatment and prognosis of these cancers." (PMID 36555359, 2022). "Several exogenous cancer-inducing factors, like Helicobacter pylori and papilloma virus 16 E7, upregulate the expression of CIP2A in host tissue which may be critical for their oncogenic activity." (PMID 33078202, 2021). "Similarly, higher SET and CIP2A levels in human CRC cancers are positively correlated with CD8+ cytotoxic T infiltration but negatively correlated with Foxp3+ Treg infiltration." (PMID 34911954, 2021). "Here, our study suggested that CIP2A inhibition could promote cell death even in cancer cells that are resistant to doxorubicin." (PMID 33948919, 2021). "This clearly demonstrated a strong upregulation of CIP2A in cancer tissue." (PMID 33078202, 2021). "High CIP2A and/or SET levels have repeatedly been associated with worse prognosis across cancers." (PMID 34129940, 2021). "In addition to its biological significance in the promotion of the malignant transformation of human cells, CIP2A also plays important roles in the development of cancers." (PMID 32321509, 2020). "The cellular PP2A inhibitors oncoprotein I2PP2A (SET) and cancerous inhibitor of PP2A (CIP2A) affect drug resistance and cell survival in many cancers; subsequently, CIP2A downregulation and SET inhibition activate PP2A and restore chemosensitivity to cisplatin as well as reduce tumor burden." (PMID 32927892, 2020). "The presence of CIP2A autoantibodies has been detected in the serum of patients with some cancers." (PMID 32321509, 2020). "A previous study has demonstrated that CIP2A could regulate the cell cycle by targeting the polo-like kinase (Plk1) and protect cancer cells from apoptosis and senescence." (PMID 32321509, 2020). "Thus, suppressing CIP2A expression not only reduces the proliferation of cancer cells, but also sensitizes them to chemotherapy." (PMID 32784981, 2020). "Targeting the oncoprotein CIP2A is an important strategy to reactivate PP2A to treat cancer." (PMID 30759826, 2019). "Although CIP2A has been suggested to influence the prognosis of various cancer types, the role of CIP2A in EGJA remains unknown." (PMID 31534561, 2019). "The aberrant expression of Cip2a has been observed in different types of cancer cells." (PMID 31762806, 2019). "In other cancer models, CIP2A promoted MYC protein levels in both of the studied AML cell lines." (PMID 31717978, 2019). "In addition, existing evidences have shown that CIP2A conductively increase cell proliferation and the growth of xenografted tumors in various cancers." (PMID 30044786, 2018). "Furthermore, PP2A inactivation in cancer also occurs frequently through the upregulation of CIP2A, a PR65 interactor and PP2A inhibitor." (PMID 29464081, 2018). "This is the first study that provides the link between ATF6 and CIP2A in cancer." (PMID 30063110, 2018). "Thus, inhibitors of SET and CIP2A were used to reduce Myc expression and activity, decreasing the tumorigenic potential of cancer cells." (PMID 28280720, 2017).
cancer (continued). "Third, given the prevalent incidence of upregulated CIP2A and Akt in various cancers, our understanding of CIP2A and lapatinib resistance may also shed light on the mechanisms of the resistance to other ErbB2-targeting drugs, such as trastuzumab." (PMID 28938602, 2017). "Furthermore, cancerous inhibitor of protein phosphatase 2A (CIP2A) has been shown to play important regulatory roles in cancer proliferation." (PMID 28521777, 2017). "However, the prognostic prediction of FN and CIP2A have been confirmed in several other types of cancers." (PMID 28521777, 2017). "On the other hand, the results also indicate that CIP2A targeting cancer therapies would not cause serious immunological side-effects." (PMID 27100879, 2016). "Moreover, although various studies have indicated the clinical relevance and prognostic value of CIP2A in various cancers, its implication as a therapeutic target for TNBC remains to be validated." (PMID 26824320, 2016). "Moreover, as an oncogenic protein in the transformation of cells and cancer progression, CIP2A has been shown to correlate with a number of drug effects in cancer." (PMID 26824320, 2016). "Our findings strengthen the evidence for the use of CIP2A as an anti-cancer target." (PMID 26824320, 2016). "The over-expression of CIP2A protein has been previously reported in a variety of cancer types." (PMID 26894380, 2016). "However, despite its emerging role as a human oncoprotein and future target for cancer therapies, very little is known about the physiological role of CIP2A." (PMID 27100879, 2016). "Furthermore, it has been shown that high levels of SET and CIP2A at diagnosis are biomarkers for cancer progression in leukemia and confer a poor prognosis." (PMID 27705940, 2016). "Among the multifaceted drug-induced events described herein, an interesting link has emerged between the oncoprotein histone deacetylase HDAC1 and the oncogenic Cancerous Inhibitor of Protein Phosphatase 2A (CIP2A) which is overexpressed in several cancers including CRCs." (PMID 27029072, 2016). "Furthermore, these findings disclose a new role for HDAC1 in governing transcription of the oncogenic Cancerous Inhibitor of Protein Phosphatase 2A (CIP2A) that is known to be overexpressed in numerous cancers including CRCs." (PMID 27029072, 2016). "Together these results support the idea that targeting of CIP2A could simultaneously be used for radiosensitation of Oct4 positive cancer stem cell-like population, as well as for eradication of the Oct4 negative bulk of the HNSCC tumor." (PMID 25474139, 2015). "These structurally unrelated agents showed a common target in different cancer cells, suggesting that CIP2A may be a novel anti-cancer target." (PMID 25537503, 2015). "Mutational data and gene expression data (pan-cancer normalized) are available for a limited number of patients only; nevertheless, KRAS activating mutations exhibited similar synergistic relationship with CIP2A expression levels as did high KRAS expression." (PMID 26278961, 2015). "Although following studies showed that the expression of CIP2A was up-regulated in a variety of cancer types ranging from solid tumor to hematological malignancies, research on the cellular functions of CIP2A under physiological conditions and in diseases states are still limited." (PMID 26560124, 2015). "The expression of CIP2A may be used as a biomarker for screening, diagnosis and prognosis in many cancers." (PMID 25650660, 2015). "Therefore, both of these evidences supported that aberrant CIP2A expression at early stage of cancer would trigger immune response." (PMID 26560124, 2015). "However, how these CIP2A targeted molecules and signaling pathways are united together in cancer progression require extensive systematic studies." (PMID 26560124, 2015). "In contrast, CIP2A expression was decreased in TA and CB cell populations in cancer." (PMID 25965834, 2015).